KIT (KIT proto-oncogene, receptor tyrosine kinase)
Diseases named in the same sentence as KIT in open-access papers (continued):
Sharing a sentence is not in itself a finding about the gene and the disease.
tumor (continued). "Noteworthily, a retrospective study suggested that the mutations in KIT exon 11 were related to multiple factors, including age, gender, primary tumor location, tumor diameter, mitotic count and CD34 positivity." (PMID 37901323, 2023). "Familial GIST is an inherited neoplastic disease with multiple GISTs throughout the GI tract caused by germline mutations in KIT gene or PDGFRA gene." (PMID 37870660, 2023). "A dysregulated KIT function, due to either overexpression or mutations, promotes tumor development and progression in various human cancers, with mutations in TGCT being the most well characterized for SE diagnosis and prognosis." (PMID 37175579, 2023). "To verify if KIT K558N is a pathogenic mutation of this tumor, we assessed protein expression status." (PMID 37215953, 2023). "Despite the reduction in AF values for the 2 KIT variants, the CT scan showed that the disease had progressed with increased tumor size." (PMID 35273917, 2022). "Surprisingly, the levels of phosphorylated SMAD2 were significantly lower in KIT-expressing versus KIT-deficient tumor cells." (PMID 35842424, 2022). "In this report, we identified the novel mutations of the c-KIT gene from the splenic tumor sample of a feline MCT, in addition to the common exon 8 insertional mutations." (PMID 36138037, 2022). "Currently, the known factors associated with prognosis are tumor size, site, nuclear split phase count, tumor rupture, positive cut margins, KIT 11 exon deletion mutations, and other adverse biological behaviors." (PMID 36620561, 2022). "In a study conducted on two dogs with documented exon-11 c-KIT mutations, imatinib mesylate (Gleevec) has been used for its ability to inhibit protein kinases and results in a marked tumor response and an increase in survival time." (PMID 35878393, 2022). "In therapy, c-KIT inhibitors were shown to have a positive response, particularly for neoplasms bearing c-KIT mutations compared with wild-type tumors." (PMID 35621644, 2022). "As an example, this technique was used to investigate SPRED1 function as a tumor suppressor in the context of KIT mutations in mucosal melanoma." (PMID 35713744, 2022). "CRISPR-Cas9-mediated deletion of the KIT gene caused a partial mesenchymal-to-epithelial phenotype switch and a strong reduction of intra-tumor stromal content." (PMID 35842424, 2022). "In archived tumor samples, 67% (68/102) had a KIT mutation; 61% (62/102) had primary KIT mutations (exons 9 and 11) and 12% (12/102) had secondary mutations (exons 13, 14, 17, and 18)." (PMID 35050442, 2022). "The biopsy was obtained from a 69-year-old male patient that had a 7-year history of a GIST tumor harboring a KIT exon 11 mutation with peritoneal metastases." (PMID 36456699, 2022). "Tumor samples taken from the brains of cancer patients were significantly more likely to have a mutation in the KIT gene." (PMID 35681762, 2022). "After imatinib treatment for four and a half months based on the mutated c-KIT gene in the biopsy specimen, the primary tumor shrank, followed by surgical resection of the tumor at a size of 8 × 5 × 5 cm." (PMID 35720122, 2022). "Vice versa, overexpression of KIT caused a partial epithelial-to-mesenchymal phenotype switch, a strong increase of intra-tumor stromal content, and high expression of TGFβ1." (PMID 35842424, 2022). "On the other hand, in the imatinib resistant model (UZLX-GIST9) with double KIT exon 11 and 17 mutations, we observed tumor volume stabilization in the dovitinib-treated group." (PMID 35625872, 2022). "Mutations in the c-KIT gene, receptor tyrosine kinase expressed on mast cells, have been reported in tumor cells of feline MCT2–5, and this is believed to be one of the causes of feline MCT." (PMID 36138037, 2022). "The KIT variant, exon 11 c.1727T>C, was the same as that reported for the corresponding plasma-derived ctDNA and tumor." (PMID 35273917, 2022).
tumor (continued). "Mechanistically, TKI resistance in GIST is largely mediated through secondary KIT mutations, indicating that active KIT continues to be the main driver of the disease during tumor progression." (PMID 35585158, 2022). "Based on these previously published data and the data presented here, it seems unlikely that a c-kit mutation in exon 8 causes a gain-of-function of KIT that would thereby stimulate increased tumor proliferation." (PMID 36136708, 2022). "In our dose-dependent sensitive model (UZLX-GIST2), which is characterized by a KIT exon 9 mutation, dovitinib indeed led to tumor shrinkage (to 45% of baseline)." (PMID 35625872, 2022). "Most GISTs have gain-of-function mutations in c-KIT or platelet-derived growth factor receptor alpha that promote tumor cell proliferation and inhibit tumor cell apoptosis." (PMID 35502427, 2022). "Surprisingly, both esophageal GISTs with trisomies (cases 57 and 288) showed the same KIT exon 13 mutation, Lys642Glu, whereas the tumor of case 79 had a KIT exon 11 mutation." (PMID 35284037, 2022). "Our results showed that known tumor mutations, including both KIT and PDGFRA, were detectable in ctDNA only among patients with metastatic GIST with measurable disease progression." (PMID 35273917, 2022). "In a model with KIT exon 11 and 17 mutations, dovitinib induced tumor necrosis, most likely due to anti-angiogenic effects." (PMID 35625872, 2022). "Patient 12 had a 10-cm rectal GIST with a mitotic count > 10 mitoses per 5 mm2 and a KIT exon 11 mutation in the tumor biopsy." (PMID 34552011, 2021). "As the main GIST drivers, gain-of-function mutations in KIT or PDGFRA are closely associated with not only tumor development and progression but also therapeutic response." (PMID 34805171, 2021). "A previous study found that masitinib caused tumor regression after brain metastasis in patients with c-KIT-mutant esophageal melanoma." (PMID 33807778, 2021). "Patients with germline mutations in KIT genes can have associate paragangliomas, dysphagia or skin hyperpigmentation, and patients with mutations in PDGFRA genes associate inflammatory fibroid polyps or intestinal fibromatosis." (PMID 34442339, 2021). "Around 80% of GISTs harbor KIT gene mutations, which would result in abnormally activation of the KIT receptor that further leads to tumor growth." (PMID 33658035, 2021). "In this study, we comprehensive analyzed genomic changes in GIST using WES, and identified a series of novel variants in KIT/PDGFRA or other tumor-related genes, and these genes are enriched in several DNA repair- or metabolism-related pathways." (PMID 34805171, 2021). "The important survival prognostic factors that pathologists describe are: tumor size and location, eventual tumor rupture, mitotic rate, c-KIT expression, and its mutation." (PMID 34503161, 2021). "Our data highlights the heterogeneity of KIT secondary mutations as the main mechanism of tumor progression in response to KIT inhibitors, in imatinib-resistant GIST patients." (PMID 34504655, 2021). "There are 9 tumor core gene variations, including the KIT gene missense mutation in p.K642E (c.1924A>G) and p.T670I (c.2009C>T), KIT gene copy number gains, and PDGFRA gene copy number gains." (PMID 34449472, 2021). "In the tumor biopsy, 21 patients displayed primary mutations in KIT exon 11, while three patients had mutations in other KIT exons." (PMID 34552011, 2021). "Knowledge of the c-KIT mutation in these neoplasms opens a wide field to explore target therapy studies in the future." (PMID 34064058, 2021). "The tumor of this dog had a novel deletion mutation c.1725_1733del within KIT and the mutation caused ligand-independent phosphorylation of KIT, which was suppressed by toceranib." (PMID 33827546, 2021). "Whole exome sequencing of tumor specimens in this patient showed a KIT gene missense mutation in p.K642E (c.1924A>G) and p.T670I (c.2009C>T), KIT gene copy number gains, and PDGFRA gene copy number gains." (PMID 34449472, 2021).
tumor (continued). "Mutations in exon 11 of KIT have been generally associated with tumours that are imatinib-sensitive while tumours with mutation in exon 9 tend to be resistant to imatinib." (PMID 33528660, 2021). "We developed patient-specific SiMSen-Seq panels that target the patient's tumor-specific mutation in either KIT or PDGFRA, as well as mutations related to imatinib and sunitinib resistance." (PMID 34552011, 2021). "Our data highlights the heterogeneity of KIT secondary mutations as the main mechanism of tumor progression to KIT inhibitors in imatinib-resistant GIST patients." (PMID 34504655, 2021). "This was especially evident in patient 1, where we only found a KRAS mutation in a punch from the primary resection of the tumor, and afterwards a KIT mutation in the extensive resection of the same tumor." (PMID 34072863, 2021). "In another patient who had significant tumor shrinkage, a K642E mutation at KIT exon 13 was found with NGS-sequencing from the residual tumor mass." (PMID 33546113, 2021). "Although somatic mutational changes within the BRAF, NRAS, NF-1, and KIT genes are seen to deregulate tumor biology within the melanocytes, acknowledgment of the contributory role of inherited factors is also due." (PMID 34155457, 2021). "One case report in 2017, underlined the benefit of imatinib in a patient showing c-KIT tumor progression following treatment with niltoinib and ipilimumab." (PMID 33918490, 2021). "The tumor-specific mutation was identified by sequencing the primary tumor, while the sequences for imatinib and sunitinib resistance in KIT and PDGFRA were identified from the COSMIC database." (PMID 34552011, 2021). "Currently, the preferred concept of SM pathogenesis is a multimutated neoplasm in which KIT mutations represent a "phenotype modifier" toward SM." (PMID 34917498, 2021). "Patients with KIT mutated GISTs tended to have a larger tumor size and a higher mitotic index and risk grade as compared with those with PDGFRA-mutant and WT GISTs." (PMID 34956906, 2021). "For example, CBL is a tumour suppressor gene involved in the process of down-regulation of the KIT receptor, and its mutation causes sustained KIT activation." (PMID 34357128, 2021). "Neoadjuvant therapy can be continued until the regression of the tumour size or metabolic activity reaches a plateau phase as the development of secondary KIT mutations is common in protracted treatment duration." (PMID 33528660, 2021). "Nine tumor-specific mutations were detected in ctDNA, one in KIT exon 9, six in KIT exon 11, and two in PDGFRA exon 18, all mutations were insertions or deletions, that is, indels." (PMID 34552011, 2021). "patients with c‐KIT mutations in advanced disease, were treated with the tyrosine kinase inhibitor imatinib and had a tumor response rate of 54% and an overall disease control rate of 77%." (PMID 33844113, 2021). "GISTs with PDGFRA exon 18 mutations had smaller tumour size than cases with KIT exon 9 and exon 11 mutations (p=0.01)." (PMID 31538651, 2020). "The D816V mutation in KIT is frequently found in the tumor cells of SM patients and is an important part of the established diagnostic criteria for ASM." (PMID 33246418, 2020). "Certain morphological features are associated with KIT 11 deletions such as gastric location, spindle cell morphology and large tumour size." (PMID 31538651, 2020). "It has been reported that PI3 kinase association can block primary mutation of KIT mediated tumor formation completely, our results suggested a difference between primary and secondary mutation of KIT mediated tumor formation." (PMID 32082541, 2020). "GISTs with KIT exon 9 mutation classification have significant linkages with tumor size more than 10 cm, a stronger enhancement grade and greater area of tumor necrosis when compared to those of the KIT exon 11 mutation classification (P < 0.05)." (PMID 33304203, 2020).
tumor (continued). "GISTs with KIT exon 9 mutations also responded well to imatinib therapy at a dosage of 600 mg daily, with obvious shrinkage of their tumor size." (PMID 32264886, 2020). "The tumor size was larger than that of other mutated types of GISTs, except GISTs with KIT exon 11 deletion involving 557/558, which was statistically significant (All of P was < .05)." (PMID 32697050, 2020). "90% of GIST tumours express gain-of-function mutations in either KIT or PDGFR genes, which code the tyrosine kinase receptors responsible for cell survival and proliferation." (PMID 31911828, 2020). "KIT mutations are frequently found in the tumor cells of SM patients and are an important part of the established diagnostic criteria for ASM, but the most prevalent variant of these is the D816V mutation, which has been observed in > 60% of ASM patients." (PMID 33246418, 2020). "Of 22 multiple sporadic GIST patients with at least one lesion assessed as intermediate and high risk mentioned in the literature, 13 cases showed tumor multiplicity on KIT/PDGFRA mutation analysis, excluding them as metastatic GISTs." (PMID 32408889, 2020). "In low‐risk GISTs, we identified two predictors of worse DFS: tumor origin in the rectum and KIT exon 11 deletion involving two or more codons." (PMID 32697050, 2020). "Genomic DNA was extracted from the paraffin-fixed tumour sample, and c.1504_1509dupGCCTAT (p.Ala502_Tyr503dup) mutation was detected in exon 9 of the KIT gene." (PMID 33281931, 2020). "TKIs block the tyrosine kinase receptors encoded by the KIT or PDGFR genes leading to tumour cell death." (PMID 31911828, 2020). "Most tumours had KIT exon 11 mutations (n = 24, 48%), followed by PDGFR exon 18 (n = 5, 10%) and KIT exon 9 (n = 4, 8%)." (PMID 31911828, 2020). "Based on the allele frequency of SDHA and KIT mutations, our tumor is best defined as SDH‐deficient GIST in which SDH loss is most likely the oncogenic driver." (PMID 31124195, 2019). "Risk analysis for KIT mutation showed a relative risk of tumor size (5–10 and >10 cm), degree of enhancement on CT imaging, and necrosis in the tumors ranging from 1.55 to 3.27." (PMID 31076599, 2019). "HQP1351 effectively overcomes the imatinib resistance induced by secondary KIT mutations and exhibits antitumor activity in xenograft tumor models of GISTs in mice." (PMID 31673329, 2019). "Young age, smaller tumor size at the initiation of imatinib, KIT exon 11 mutation, surgical intervention, and period 2 were favorable factors for PFS and OS." (PMID 30693663, 2019). "One tumor (patient #7) was found to have a disease associated variant HRAS c.182A > G p.(Q61R) as well as variants of uncertain significance in KIT c.287C > T p.(T96 M) and PTCH1 c.3617G > A p.(R1206H)." (PMID 31046843, 2019). "The KIT–9 group was statistically associated with a tumor size larger than 10 cm and a higher enhancement ratio when compared with those of the KIT–11 group (both P < 0.05)." (PMID 31076599, 2019). "Our data highlight that heterogeneity of KIT secondary mutations is the main mechanism of tumour progression to KIT inhibitors in imatinib-resistant GIST patients." (PMID 30792533, 2019). "Although GISTs generally remain dependent on oncogenic KIT during tumor progression, KIT mutations alone are insufficient to induce malignant behavior." (PMID 30867899, 2019). "Unfortunately, initially sensitive tumours acquired imatinib resistance due to a KIT secondary mutation." (PMID 31552107, 2019). "In multivariate analysis, tumor size (β = 0.206; P = 0.022) and KIT–9 (β = 0.389; P = 0.006) were independent factors associated with tumor necrosis." (PMID 31076599, 2019). "High expression levels of MALAT1 in paraffin tumor tissue have been detected in 8 out of 16 (50%) GIST patients harboring c-KIT mutations as compared to 1 out of 4 (25%) wild-type patients." (PMID 31827510, 2019).
tumor (continued). "Among 360 patients with available tumor specimens that were examined before imatinib treatment, 318 (88.3%) had KIT or PDGFRA mutation and the wild type was observed in 29 patients (8.1%)." (PMID 30693663, 2019). "The Notch signalling pathway has also been reported to be a tumour suppressor in GIST cells harbouring a KIT mutation." (PMID 31552107, 2019). "In plasma ctDNA collected before start of treatment in eight patients with localized disease and a tumor KIT exon 11 mutation, only one patient (sample 7) had a detectable mutation in the ctDNA." (PMID 29568401, 2018). "Molecular analysis revealed that the tumor harbored a deletion mutation in exon 11 of KIT, and preoperative imatinib therapy was recommended." (PMID 30313116, 2018). "KIT mutations have been evaluated in various other tumors, and in some neoplasms they are an important prognostic factor." (PMID 29796159, 2018). "In this study, an in-house designed single ddPCR assay was able to detect multiple mutations in KIT exon 11 with high sensitivity (95%) and specificity (100%) in tumor biopsies of patients with GIST." (PMID 29568401, 2018). "For example, the loss-of-function SDH complex mutations are considered to play a critical role in tumor initiation of a minor subset of GISTs that exhibit distinct clinicopathological features from GISTs with KIT- or PDGFRA-mutations." (PMID 30388854, 2018). "Tumor infiltration by these immune cells was associated with improved progression-free survival in association with KIT exon 11 mutations." (PMID 28428884, 2017). "Specific mutations in the so-called KIT oncogene are the most common cause of the development of this tumor." (PMID 28058590, 2017). "Secondary objectives included evaluation of antitumor activity of the combination based on KIT mutation status and the capacity of tumor-associated immune biomarkers to predict response." (PMID 28428884, 2017). "Even more, comparative analysis of dasatinib vs. crenolanib with regard to inhibition of KIT D816V in the isogenic cellular background of Ba/F3 cells reveals higher potency of crenolanib, underlining its potential clinical use in mutant-KIT neoplasms." (PMID 29137311, 2017). "Histological diagnosis of GIST was supported by strong CD117 staining and the identification of an activating KIT mutation (p.W557_K558del) in the tumor tissue." (PMID 28768491, 2017). "Many secondary KIT mutations have been found at low frequencies, and mutations often exhibit inter-tumor or even intra-tumor heterogeneity in the same patient." (PMID 28947997, 2017). "GISTs were identified as tumors of the interstitial cells of Cajal, or their precursors, with more than 75 % showing mutations in KIT, thus defining a specific sarcoma subtype." (PMID 27586263, 2016). "Conversely, KIT exon 11 mutations have been found in mitotically inactive GISTs of 1 cm or smaller, suggesting that oncogenic KIT activity contributes to early tumor growth." (PMID 27443349, 2016). "Specifically, PIK3CA and KIT mutations were detected in 16 (47.0%), and 8 (23.5%), respectively, of the tumor specimens." (PMID 26968814, 2016). "KIT mutation analysis of the resected tumor specimen showed an in-frame deletion of a portion of the juxtamembrane domain (exon 11)." (PMID 27586263, 2016). "Liver metastases developed 5 months later and following disease progression on dacarbazine (1000 mg/m2, two cycles), given that a KIT p.L576P mutation was present in the primary tumour biopsy, imatinib was administered (400 mg/day)." (PMID 27502704, 2016). "Specifically, KRAS, PIK3CA and KIT mutations were detected in 31/48 (64.6%), 11/48 (22.9%), 8/48 (16.7%) tumor specimens, respectively." (PMID 26968814, 2016). "This position was also the most frequently mutated residue found in imatinib-resistant KIT mutants from analysis of tumor samples obtained from patients enrolled in a Phase II clinical study of imatinib." (PMID 27556159, 2016).